RNU6-1263P (RNA, U6 small nuclear 1263, pseudogene)
Gene: Small nuclear RNA gene on chromosome 3 (98,908,459 to 98,908,564, forward strand). Ensembl gene ENSG00000207331.
Homologues: Orthologues: chimpanzee U6 (100% identical), macaque U6 (92% identical), rat LOC120096093 (91% identical), rabbit U6 (84% identical), rabbit U6 (77% identical). Paralogues in human: RNU6-15P (93% identical), RNU6-1 (92% identical), RNU6-2 (92% identical), RNU6-3P (92% identical), RNU6-4P (92% identical), RNU6-5P (92% identical), RNU6-6P (92% identical), RNU6-9 (92% identical), RNU6-10P (91% identical), RNU6-12P (91% identical), RNU6-13P (91% identical), RNU6-16P (91% identical), and 1285 more.